BTG1 (BTG anti-proliferation factor 1)
Description:
Anti-proliferative protein.
Synonyms: APRO2
Tractability: No criterion of Open Targets' tractability assessment is met for any kind of drug.
Gene: Protein-coding gene on chromosome 12 (92,140,278 to 92,145,846, reverse strand). Ensembl gene ENSG00000133639.
Subcellular location (Human Protein Atlas): Nucleoplasm; Cytosol
Pathways (Reactome):
Gene expression (Transcription): FOXO-mediated transcription of cell cycle genes
Gene Ontology:
Molecular function: enzyme binding; protein binding; kinase binding; transcription coregulator activity
Biological process: negative regulation of cell population proliferation; positive regulation of angiogenesis; positive regulation of endothelial cell differentiation; positive regulation of fibroblast apoptotic process; positive regulation of myoblast differentiation; cell migration; negative regulation of cell growth; regulation of DNA-templated transcription
Cellular component: cytoplasm; nucleus; nucleoplasm
Genetic constraint (gnomAD): Loss-of-function variants: 2 observed, 13.74 expected, observed/expected ratio (o/e) 0.15, 90% interval 0.059 to 0.46. The synonymous counts are far from expectation, so gnomAD's model fits this gene poorly and the ratio says little. Missense variants: 149 observed, 209.29 expected, observed/expected ratio (o/e) 0.71, 90% interval 0.62 to 0.82. Synonymous variants: 109 observed, 80.44 expected, observed/expected ratio (o/e) 1.36, 90% interval 1.16 to 1.59.
Homologues: Orthologues: chimpanzee BTG1 (100% identical), mouse Btg1 (100% identical), dog BTG1 (99% identical), guinea pig BTG1 (99% identical), pig BTG1 (99% identical), rat Btg1 (99% identical), rabbit BTG1 (91% identical), rat Btg1b (83% identical), rat Btg1c (82% identical), zebrafish btg1 (70% identical), tropical clawed frog btg1 (61% identical). Paralogues in human: BTG2 (61% identical), BTG3 (32% identical), BTG4 (29% identical).
Diseases named in the same sentence as BTG1 in open-access papers:
BTG1 is named in the same sentence as 87 diseases in open-access papers, as found by Europe PMC text mining. Sharing a sentence is not in itself a finding about the gene and the disease. The quoted sentences say what the papers report.
breast carcinoma (18 papers, 2013 to 2023). "Some studies have indicated that low KMT2D transcript levels or decreased BTG1 protein expression are associated with poor survival in breast cancer." (PMID 37650999, 2023). "TCGA data showed that BTG1 expression was positively associated with a high overall survival rate of breast cancer patients (Figure 3Gp < 0.05)." (PMID 36339000, 2022). "The expression of BTG1 is also low in breast cancer, and its overexpression has been associated with radiation therapy." (PMID 33041670, 2020). "Here, we found that BTG1 mRNA expression was remarkably linked to the infiltration of immune cells, Her2 expression and molecular subtyping of breast cancer, demonstrating that BTG1 would be employed to guide the target therapy for breast cancer patients." (PMID 36339000, 2022). "BTG1 expression was negatively correlated with favorable prognosis of gastric, lung or ovarian cancer patients, but the converse was true for breast cancer (p < 0.05)." (PMID 36339000, 2022). "BTG1 methylation was higher in breast cancer than normal tissues (p < 0.05), N1 than N0, and Luminal than triple-negative breast cancer (TNBC) patients (p < 0.05) by UALCAN." (PMID 36339000, 2022). "In breast cancer, the relation of BTG1 expression to TNM staging was the opposite to that between BTG1 methylation and TNM staging." (PMID 36339000, 2022). "TCGA database showed that BTG1 expression was negatively associated with lymph node metastasis and TNM staging of breast cancer (p < 0.05)." (PMID 36339000, 2022). "BTG1 showed low expression in breast cancer, colorectal cancer, leukemia, lymphoma, ovarian cancer, and sarcoma." (PMID 33041670, 2020). "BTG1 hypoexpression was reported to significantly correlate with aggressive features and worse prognosis of thyroid cancer, esophageal cancer, breast cancer, non-small cell lung cancer, and skin squamous carcinoma." (PMID 33330092, 2020). "BTG1 overexpression was observed to inhibit migration and invasion of breast cancer cells with MMP-2 and -9 hypoexpression and E-cadherin hyperexpression." (PMID 33330092, 2020). "A previous study documented that overexpression of BTG1 induces apoptosis of breast carcinoma cells, accompanied by a decline in the Bcl-2 level and an increase in the Bax and Caspase 3 levels." (PMID 31324015, 2019). "In survival analyses based on Kaplan-Meier Plotter, TOB1, BTG1 and BTG4 showed significant associations with survival outcome of different subtypes of breast cancer." (PMID 28922388, 2017). "The upregulated miR-183 in our samples was predicted to be responsible for the decrease in expression of the BTG1 mRNA whose protein is involved in cell cycle arrest and apoptosis in breast cancer cells." (PMID 29203780, 2017). "Further study shows that BTG1 functions as Bcl-2-regulated mediator and is involved in antisense Bcl-2-mediated cytotoxic effects in breast cancer cells." (PMID 27447746, 2017). "BTG1 has been reported as a tumor suppressor inhibiting tumor proliferation and migration and increasing anti-tumor therapy sensitivity in some kinds of tumors, including breast cancer." (PMID 36998462, 2023). "The correlation of BTG1 mRNA expression with clinicopathological features of breast cancer." (PMID 36339000, 2022). "Additionally, TCGA data showed the same results about the prognostic significance of BTG1 expression to Kaplan-Meier plotter’s in gastric and breast cancers although Kaplan-Meier plotter is based on cDNA array and the TCGA experiment on RNA sequencing." (PMID 36339000, 2022). "KEGG analysis demonstrated that the BTG1-related pathways included cytokine-cytokine receptor interaction, cell adhesion molecules, chemokine, immune cell receptor and NF-κB signal pathways in gastric and breast cancers." (PMID 36339000, 2022).
breast carcinoma (continued). "BTG1 expression was down-regulated in breast cancer cells and significantly correlated with proliferation, poor overall survival, histological grade, clinic stage, and lymph node metastasis by regulating protein expression levels of Cyclin-D1, Bcl-2, and MMP-9." (PMID 29416786, 2018). "The down-regulated expression of BTG1 was detected in both lung and breast cancers." (PMID 27447746, 2017). "Furthermore, BTG1 mRNA is downregulated in several solid tumors, including thyroid, lung, nasopharyngeal and breast cancer, while decreased expression is correlated with poor overall survival or increased cellular invasion." (PMID 26657730, 2016). "Moreover, BTG1 expression was positively correlated with dedifferentiation and histological grading of gastric cancer, and venous invasion, lymphatic invasion, and TNM staging of ovarian cancer, but negatively associated with lymph node metastasis and TNM staging of breast cancer." (PMID 36339000, 2022). "In breast cancer cells (MCF-7 and MDA-MB-231), overexpression of BTG1 inhibited cell proliferation, induced G0/G1 cell cycle arrest, and promoted apoptosis." (PMID 35761157, 2022). "According to the Kaplan-Meier plotter, we found that BTG1 expression was negatively correlated with favorable prognosis of gastric, lung, or ovarian cancer patients, but not for breast cancer patients." (PMID 36339000, 2022). "Both BTG1 and BTG2 may act as the negative regulator to breast cancer cells." (PMID 29416786, 2018).
leukemia (12 papers, 2012 to 2025). A malignant (clonal) hematologic disorder, involving hematopoietic stem cells and characterized by the presence of primitive or atypical myeloid or lymphoid cells in the bone marrow and the blood. "Evidence shows that there are characteristics exclusive to specific leukemias, including deletion of BTG1 in B-cell leukemia, loss of IKZF1 with monosomy 7 in AML, and deletions involving IGH, TCR, IKZF1, and CDKN2A/B in CML-AP/CP." (PMID 27233483, 2016). "We recently reported that in BCP-ALL, BTG1 regulates the glucocorticoid receptor (GR)-dependent transcriptional response in leukemia cells, while loss of BTG1 expression leads to glucocorticoid resistance in cell line models." (PMID 22359517, 2012). "Indeed, we recently showed that in a mouse model, loss of Btg1 cooperates with deletions of the tumor suppressor Ikfz1 to promote leukemia development." (PMID 30350856, 2019). "BTG1 negatively regulates cell proliferation and BTG1 mutations are associated with leukemias." (PMID 25710169, 2015). "A deletion on chromosome 12q21.33 (260 kb) was found in the region encoding the ALL-associated gene BTG1, whereas three deletions were found on chromosome 18, one at q21.1 and two at q23, including the 132-kb deletion affecting exon 10 of the leukemia-associated gene NFATC1." (PMID 38777370, 2024). "Disease incidence increases while time‐to‐leukemia is shortened when either one or both copies of the Btg1 gene are deleted." (PMID 30350856, 2019). "Because illegitimate RAG-mediated recombination has been implicated in the origin of several translocations and deletions in leukemia, we examined the sequences flanking each of the BTG1 breakpoints for the presence of recombination signal sequences (RSS)." (PMID 22359517, 2012). "Additionally, BTG1 and MRPS30, whose inactivation has been linked to venetoclax resistance in leukemia cell lines, exhibited decreased expression." (PMID 40709247, 2025). "Moreover, we observed similar regulation of BTG1 mRNA levels in human peripheral blood mononuclear cells (PBMCs) as well as leukemia cell lines treated with various stress-inducing agents." (PMID 26657730, 2016). "In addition, we have shown that leukemia clones carrying BTG1 deletions can survive therapy and rearise as a predominant clone in relapse or, as shown also by others, can occur as new lesions in relapse." (PMID 22359517, 2012). "On the other hand, our findings allow a better understanding of the role of BTG1 and IKZF1 deletions in modulating glucocorticoid response, thus helping to unravel the resistance phenomenon in leukemia cells displaying this genotype." (PMID 39095315, 2024).
gastric cancer (10 papers, 2015 to 2024). A primary or metastatic malignant neoplasm involving the stomach. "In line with the data about gastric cancer, BTG1 expression was positively linked to aggressive features of colorectal cancer, including depth of invasion, venous invasion, lymph node metastasis, and TNM staging." (PMID 33330092, 2020). "Down-regulated BTG1 mRNA expression in gastric cancer and hepatocelluar carcinoma was significantly associated with shorter disease-specific and recurrence-free survival as an independent prognostic factor." (PMID 33330092, 2020). "In the present study, intestinal- and diffuse-type carcinomas showed a lower BTG1 expression than aggressive mixed-type ones, in consistence with the positive association between BTG1 expression and aggressive behaviors of gastric cancer." (PMID 26050197, 2015). "However, BTG1 protein expression was positively associated with poor prognosis of gastric cancer, in agreement with our data of BTG1 mRNA expression according to TCGA databases." (PMID 33330092, 2020). "In TCGA data, BTG1 expression was positively correlated with dedifferentiation and histological grading of gastric cancer (p < 0.05)." (PMID 36339000, 2022). "According to the TCGA data, BTG1 mRNA expression was negatively related to the overall survival of the gastric cancer patients (p < 0.05)." (PMID 36339000, 2022). "The UALCAN showed that BTG1 methylation was higher in gastric cancer than in normal tissues (p < 0.05)." (PMID 36339000, 2022). "According to Wang’s database, we found that BTG1 mRNA expression was lower in gastric cancer than in normal tissues (p < 0.05)." (PMID 36339000, 2022). "In gastric cancer, lncRNA DGCR5 is known for its function as a ceRNA (competing endogenous RNA) of PTEN and BTG1 through miR-23b to inhibit the capacity of gastric cancer cells to proliferate, invade, and migrate while promoting the apoptosis of these cells." (PMID 33085646, 2020). "BTG1 hypoexpression was observed in gastric cancer and negatively correlated with depth of invasion, lymphatic and venous invasion, lymph node metastasis, TNM staging and worse prognosis of gastric cancer." (PMID 27447746, 2017). "In our another report, a positive link between BTG1 expression and poor survival of gastric cancer patients was found, which depended upon invasive depth of the cancers." (PMID 28407690, 2017). "Compared with NNM, BTG1 expression was reduced in gastric cancer, indicating that down-regulated BTG1 expression promoted the malignant transformation of gastric epithelial cells." (PMID 26050197, 2015). "BTG1 overexpression suppressed tumor growth and lung metastasis of gastric cancer cells by inhibiting proliferation, enhancing autophagy and apoptosis in xenograft models." (PMID 26050197, 2015). "BTG1 protein was expressed in gastric cancer or epithelial cells at different levels by Western blot." (PMID 26050197, 2015). "Decreased BTG1 expression in gastric cancer was positively correlated with depth of invasion, lymphatic and venous invasion, lymph node metastasis, TNM staging and worse prognosis, but the lower BTG1 expression in ovarian cancer was positively correlated with FIGO staging." (PMID 36339000, 2022). "Our previous study demonstrated that BTG1 overexpression inhibited proliferation, tumor growth or lung metastasis, induced differentiation, autophagy, apoptosis, or mediated chemosensitivity in colorectal and gastric cancer cells." (PMID 33330092, 2020). "lncRNA DGCR5 can be used as a ceRNA for BTG1 to inhibit the progression of gastric cancer." (PMID 33041670, 2020). "Our previous work has shown that BTG1 overexpression inhibited proliferation, migration, invasion, tumor growth, lung metastasis, and induced G2/M arrest, differentiation, senescence, apoptosis and chemosensitivity in gastric cancer cells." (PMID 27447746, 2017).
gastric cancer (continued). "To clarify the roles of BTG1 in gastric carcinogenesis and subsequent progression, we examined the expression of BTG1 mRNA and protein, and its promoter methylation in gastric cancer tissues, and compared them with the clinicopathological and prognostic parameters of the cancers." (PMID 26050197, 2015). "BTG1 overexpression might reverse the aggressive phenotypes and be employed as a potential target for gene therapy of gastric cancer." (PMID 26050197, 2015). "BTG1 expression was restored after 5-aza-2′-deoxycytidine treatment in gastric cancer cells." (PMID 26050197, 2015). "In addition, we focused on the effects of BTG1 overexpression on the aggressive phenotypes of gastric cancer cells and clarified the relevant molecular mechanisms." (PMID 26050197, 2015). "BTG1 might be employed as a potential target for gene therapy for gastric cancer." (PMID 26050197, 2015). "Therefore, we speculate that BTG1 overexpression in more aggressive gastric cancers might be a reactive up-regulation and inhibit aggressive phenotypes of cancer cells in a negative feedback manner." (PMID 26050197, 2015). "BTG1 was reported to protect cells from oncogenic transformation; IGFBP7+ CAF was reported to promote gastric cancer; CAF-derived MFAP5 activated cell growth and migration in oral tongue squamous cell carcinoma via activation of MAPK and AKT pathways." (PMID 38686196, 2024). "The four constituents of the expression panel, MAGED2, SYT8, BTG1, and FAM46, have individual roles in gastric cancer progression." (PMID 29721160, 2018). "In gastric cancer, the downregulation of BTG1 leads to poor prognosis, especially in cases of proximal non-diffused and diffuse gastric cancer." (PMID 33041670, 2020). "BTG1 protein was detected in gastric cancer and adjacent non-neoplastic mucosa (NNM) at an approximately equal level (p > 0.05)." (PMID 26050197, 2015). "In addition, ectopic BTG1 expression enhanced the chemosensitivity of gastric cancer cells to SAHA, MG132, cisplatin and paclitaxel, which was positively correlated with BTG1-induced apoptosis and lower expression of chemoresistant genes." (PMID 26050197, 2015). "BTG1 expression was statistically lower in gastric cancer than non-neoplastic mucosa and metastatic cancer in lymph node (p < 0.05)." (PMID 26050197, 2015). "Compared with NNM, decreased BTG1 mRNA expression was seen in 57.4% (13/23) of gastric cancers, while there was no statistical difference between gastric cancer and paired NNM." (PMID 26050197, 2015).